U3 (Small nucleolar RNA U3 )
Synonyms: LOC124901858
Gene: Small nucleolar RNA gene on chromosome 7 (25,264,656 to 25,264,882, forward strand). Ensembl gene ENSG00000202233.
Gene Ontology:
Biological process: RNA processing
Cellular component: nucleolus
Homologues: Orthologues: chimpanzee U3 (94% identical), macaque U3 (78% identical), rabbit U3 (67% identical), rat U3l1 (51% identical). Paralogues in human: SNORD3P1 (77% identical), U3 (77% identical), U3 (76% identical), U3 (75% identical), SNORD3E (73% identical), U3 (73% identical), U3 (72% identical), SNORD3D (71% identical), SNORD3G (71% identical), SNORD3H (71% identical), U3 (71% identical), U3 (70% identical), and 11 more.